FGF23 (fibroblast growth factor 23)
Diseases named in the same sentence as FGF23 in open-access papers (continued):
Sharing a sentence is not in itself a finding about the gene and the disease.
left ventricular hypertrophy (continued). "In this sense, FGF-23 has been related with endothelial dysfunction, increased arterial stiffness, high atherosclerosis burden in the community, vascular calcification, left ventricular hypertrophy, and progression of renal disease." (PMID 24748388, 2014). "FGF23 is presumed to exert extrarenal manifestations, including left ventricular hypertrophy and cardiac systolic dysfunction." (PMID 25200959, 2014). "In animal models, FGF23 can directly induce left ventricular hypertrophy, which can be prevented by blocking the intracellular signaling pathway stimulated by FGF23." (PMID 24885942, 2014). "As such, FGF23 was reported to exert Klotho-independent effects in the myocardium and directly contribute to left ventricular hypertrophy, a prevalent manifestation and well-established cardiovascular risk factor in CKD." (PMID 23577141, 2013). "FGF-23 directly induces left ventricular hypertrophy in normal mice and stimulates hypertrophy of isolated cardiac myocytes, suggesting that the heart is a target tissue for FGF-23 action." (PMID 24019880, 2013). "FGF23 injected directly into the left ventricular myocardium in mice led to the development of left ventricular hypertrophy." (PMID 24046748, 2013). "One role of FGF-23 in cardiovascular disease is via induction of left ventricular hypertrophy; FGF-23 injected into mice at concentrations of 800 RU/ml resulted in LVH." (PMID 24148285, 2013). "Most recently, strong evidence suggested a direct role for FGF23 as an inducer of left ventricular hypertrophy in a mouse model." (PMID 22530966, 2012). "Recent evidence however does suggest that FGF23 is directly involved in the evolution of pathological left ventricular hypertrophy in mice." (PMID 22530966, 2012). "Beyond being a biochemical marker, phosphate overload triggers NOX-derived reactive oxygen species (ROS), activates Wnt/β-catenin and TGF-β signaling, and disrupts the FGF23–Klotho axis, promoting endothelial dysfunction, vascular calcification, and left ventricular hypertrophy (LVH)." (PMID 41516280, 2025). "Kidney-independent effects of FGF23, including induction of left ventricular hypertrophy, may play a role in this respect." (PMID 40483378, 2025). "In clinical studies, increased FGF23 has been correlated with detrimental cardiovascular remodeling, specifically concerning the onset of left ventricular hypertrophy, alterations in myocyte calcium handling, upregulation of the renin–angiotensin system and facilitation of vascular calcification." (PMID 40863356, 2025). "Elevated levels of fibroblast growth factor 23 (FGF23) are associated with left ventricular hypertrophy and heart failure in individuals with and without kidney disease." (PMID 39560998, 2025). "Whether fibroblast growth factor 23 (FGF23) directly induces left ventricular hypertrophy (LVH) remains controversial." (PMID 38174329, 2023). "FGF-23 has been shown to directly affect myocardial cells and induce left ventricular hypertrophy." (PMID 35366800, 2022). "The administration of FGF-23 directly induced left ventricular hypertrophy in mice." (PMID 35008591, 2021). "Several experimental and epidemiological studies in CKD have illustrated correlations between high FGF23 levels and various deleterious effects, including left ventricular hypertrophy, vascular calcification, impaired immune system, anemia, and decreased bone mineralization." (PMID 34678981, 2021). "In addition, FGF23 suppression by the calcimimetic etelcalcetide inhibited progression of left ventricular hypertrophy in patients on hemodialysis, also supporting a direct pro-hypertrophic action of FGF2341." (PMID 34290280, 2021). "FGF23 has been identified as a mediator of left-ventricular hypertrophy." (PMID 34572066, 2021). "FGF-23 has been shown to directly induce left ventricular hypertrophy." (PMID 34222283, 2021).
left ventricular hypertrophy (continued). "FGF23 preferentially stimulates left ventricular hypertrophy and inhibition of Klotho augments myocardial fibrosis, but whether FGF23 would promote renal fibrosis remains unclear." (PMID 33460402, 2021). "Moreover, it is worth mentioning that CharXgen significantly lowered FGF23 levels, which is markedly elevated in CKD, and elevated FGF23 levels are associated with CVD events, left ventricular hypertrophy and with increased progression of CKD." (PMID 32070049, 2020). "There are epidemiological data linking FGF23 and left ventricular hypertrophy (LVH)." (PMID 32130720, 2020). "FGF23 has been described to have effects on the heart, promoting left ventricular hypertrophy (LVH); the liver, leading to production of inflammatory cytokines; the bones, inhibiting mineralization; and the bone marrow, by reducing the production of erythropoietin (EPO)." (PMID 30909513, 2019). "Experimental data have shown that FGF23 can have a direct effect on the heart, by inducing left ventricular hypertrophy (LVH), and pathologically interfering with calcium fluxes in cardiomyocytes out of and into the sarcoplasmic reticulum, both effects not depending on phosphate." (PMID 31505780, 2019). "Furthermore, FGF-23 counteracted the beneficial effect of paricalcitol on left ventricular hypertrophy, by modulation of the calcineurin/nuclear factor of activated T cell (NFAT) pathway in a rat model of CKD." (PMID 31551803, 2019). "Different from the development of left ventricular hypertrophy, where it is complicated in a clinical setting to disentangle effects of FGF23 and phosphate, the development of vascular calcification seems to be a more straightforward consequence of high phosphate exposure, but not of FGF23." (PMID 31505780, 2019). "Some of the repeatedly documented mechanisms, though remaining speculative, include the direct cytotoxic effects of excess FGF23 on the myocardium leading to left ventricular hypertrophy, endothelial dysfunction, and arterial calcification." (PMID 31107896, 2019). "For example, FGF-23 may activate the renin-angiotensin-aldosterone system (RAAS), which is linked to a multitude of pathologic processes, including left ventricular hypertrophy, through suppression of 1,25(OH)2D, which would increase renin expression." (PMID 30120363, 2018). "Furthermore, recent studies have identified activation of FGFR4 as the primary event facilitating the effects of FGF23 on left ventricular hypertrophy, thus postulating novel mechanistic insights and therapeutic targets." (PMID 28974056, 2017). "Increased serum levels of the phosphaturic hormone FGF23 have been associated with progression of CKD, vascular calcification, left ventricular hypertrophy, and cardiovascular mortality; however, the impact of FGF23 on vascular calcification remains controversial." (PMID 29038882, 2017). "Fibroblast growth factor 23 (FGF23) has been reported to induce left ventricular hypertrophy, but it remains unclear whether FGF23 plays a role in cardiac fibrosis." (PMID 27579618, 2016). "Furthermore, a study with animal data showed that FGF23 induces left ventricular hypertrophy via FGF receptor-dependent activation." (PMID 26604925, 2015). "Experimental studies support that FGF23 induces left ventricular hypertrophy." (PMID 25112372, 2014). "In analogy to Hyp mice, it is conceivable that chronically increased plasma volume due to FGF23-induced Na+ retention may contribute to the development of left ventricular hypertrophy in XLH patients." (PMID 24797667, 2014). "The recent report by Faul and coworkers suggested that FGF23 may induce left ventricular hypertrophy by a direct, Klotho-independent action on cardiomyocytes." (PMID 24797667, 2014).
left ventricular hypertrophy (continued). "Elevated circulating concentrations of FGF23 have been implicated as a potential contributor to the development of congestive heart failure, left ventricular hypertrophy, atrial fibrillation, and hypertension, regardless of the presence or absence of impaired kidney function." (PMID 41038963, 2025). "In addition, excessive elevation of FGF23 may also lead to complications such as left ventricular hypertrophy and cardiovascular events." (PMID 39558979, 2024). "Since elevated FGF23 was found to be associated with increased cardiovascular mortality and all-cause mortality, we speculated that INHD might attenuate left ventricular hypertrophy and reduce mortality through lowering the serum FGF23 due to modification of CKD–MBD parameters." (PMID 35801203, 2022). "In addition to promoting left ventricular hypertrophy, which can lead to arrhythmias and sudden cardiac death, other proposed direct pathological effects of FGF-23 include promoting endothelial dysfunction, pro-fibrotic effects, pro-inflammatory effects, and impaired immunity." (PMID 31246994, 2019). "While it was reported that FGF23 signals in a Klotho-independent fashion through FGFR4/nuclear factor of activated T cells/calcineurin, which may cause left ventricular hypertrophy, it has not been shown how FGF23 can activate FGF receptor without Klotho." (PMID 29515522, 2018). "In addition, FGF23 may contribute to left ventricular hypertrophy by a direct, Klotho‐independent action on cardiomyocytes." (PMID 25858796, 2015). "Indeed, FGF23 may contribute to pathological left ventricular hypertrophy in a Klotho-independent manner." (PMID 24348262, 2013). "Because FGF23 was recently shown to promote pathological growth of the myocardium and proposed as a mediator of left ventricular hypertrophy through calcineurin-dependent mechanisms, we speculated that this pathway might also be activated by FGF23 in the parathyroids." (PMID 24348262, 2013). "Diminished α-Klotho—linked to both declining eGFR and protein-bound uremic toxins—raises fibroblast growth factor 23 (FGF23) levels, worsening vascular dysfunction and left ventricular hypertrophy." (PMID 40149704, 2025). "But in heart muscle, the PLCγ-calcineurin pathway is dominant, and FGF23 increases the nuclear factor of activated T cells (NFAT) and enhances left ventricular hypertrophy." (PMID 40559238, 2025). "One of the first to be described was left ventricular hypertrophy (LVH), observed in the hearts of experimental rats that suffered hypertrophy after intramyocardial injection of a solution containing FGF23." (PMID 41426862, 2025). "Our prior research, focusing on FGF23 as a biomarker for cardiac impairment, revealed cardiac changes in pediatric CKD patients, particularly highlighting left ventricular hypertrophy and impaired systolic function among those with CKD stage 2 and higher." (PMID 39433982, 2024). "Our previous study in children with CKD stages 2 to 5D showed that FGF23 levels increased as early as CKD stage 2 and were correlated with left ventricular hypertrophy and severe cardiac impairment." (PMID 39433982, 2024). "FGF23 is concentration-dependent and positively correlated with CKD progression, heart failure, vascular calcification, left ventricular hypertrophy and mortality in CKD patients." (PMID 33895867, 2021). "Higher FGF23 levels, even in individuals without renal insufficiency, correspond to an increased risk of cardiovascular mortality in the normal population, and cardiovascular risk factors including vascular dysfunction, atherosclerosis, and left ventricular hypertrophy." (PMID 28977159, 2017). "Thus, FGF-23 may directly influence cardiac remodeling, leading to left ventricular hypertrophy." (PMID 26462160, 2015). "High FGF23 levels can act through FGFR4 to promote pathological left ventricular hypertrophy independent of α‐klotho." (PMID 40464156, 2025).
left ventricular hypertrophy (continued). "Recent basic research has indicated that cardiac hypertrophy (particularly left ventricular hypertrophy) can lead to an increase in FGF23 production originating from cardiomyocytes rather than from osteocytes, thereby elevating circulating FGF23 levels." (PMID 41038963, 2025). "The induction of left ventricular hypertrophy is, however, solely mediated by FGF23 without the involvement of Klotho, whereas vitamin D partly overcomes the FGF23 effect on cardiac hypertrophy." (PMID 30921339, 2019). "In the heart, FGF-23 induces left ventricular hypertrophy independent of its co-factor, klotho, and in vascular smooth muscle cells, FGF23 inhibits vascular calcification, an effect that is klotho-dependent." (PMID 24019880, 2013). "In clinical practice, an association between increased FGF23 levels and left ventricular hypertrophy (LVH) has been observed independently of renal involvement, both in patients with normal FGF23 levels and no CKD, and in those with increased FGF23 levels in the context of CKD." (PMID 38732094, 2024). "Fibroblast growth factor 23 (FGF-23) and its coreceptor, α-Klotho, are key factors in phosphate homeostasis, and their dysregulation is an essential link between osteodystrophy, left ventricular hypertrophy, atherosclerosis, systemic inflammation, and renal fibrosis observed in patients with ESKD." (PMID 35602513, 2022). "Hence, FGF23 levels rise as kidney function declines, with the result that in patients with end state kidney disease (ESKD), FGF23 contributes to hypertension, vascular calcification, and left ventricular hypertrophy by distinct mechanisms." (PMID 34113631, 2021). "Mechanistically, FGF23 can bind and activate fibroblast growth factor receptor (FGFR) 4 independently of α-klotho, the canonical co-receptor for FGF23 in the kidney, which stimulates left ventricular hypertrophy and hepatic production of inflammatory cytokines." (PMID 31575945, 2019). "Furthermore, intramyocardial administration of FGF23 resulted in left ventricular hypertrophy in the absence of klotho." (PMID 28870151, 2017). "However, enhanced FGF-23 and PTH levels may also favor vascular damage, and left ventricular hypertrophy." (PMID 27171378, 2016). "Thus, based on current available data we hypothesize that FGF23 predicts cardiovascular outcomes in CKD mainly by portraying vascular stress due to parallel changes in mineral metabolism and by directly promoting left ventricular hypertrophy (LVH)." (PMID 23577141, 2013). "Furthermore, FGF-23 plasma levels were compared in patients with PH, dilated cardiomyopathy (DCM), left ventricular hypertrophy (LVH) in severe aortic stenosis, and controls without any LV or RV abnormalities." (PMID 36790465, 2023). "However, a direct contribution of FGF-23 to myocardial disease is still under debate, after two further experimental studies failed to confirm a role of FGF-23 in left ventricular hypertrophy." (PMID 25528363, 2014).
osteomalacia (194 papers, 2010 to 2026). Disorder caused by an interruption of the mineralization of organic bone matrix leading to bone softening, bone pain, and weakness. "Elevated FGF23 levels underlie FGF23-related hypophosphatemic rickets and tumor-induced osteomalacia." (PMID 41869037, 2026). "X-linked hypophosphataemia and tumour-induced osteomalacia are rare, distinct metabolic conditions that can affect both children and adults, and result in elevated fibroblast growth factor-23 levels and subsequent low phosphate levels." (PMID 42273000, 2026). "Phosphaturic mesenchymal tumor (PMT) is a very rare type of mesenchymal tumor that is associated with osteomalacia as a result of overexpression of fibroblast growth factor 23 (FGF23)." (PMID 40563544, 2025). "In the FGF-23-dependent forms of X-linked hypophosphatemia and tumor-induced osteomalacia, burosumab has proven to be an effective and safe drug." (PMID 41008628, 2025). "Tumor-induced osteomalacia is caused by increased levels of FGF23, usually secreted by a mesenchymal tumor." (PMID 39888445, 2025). "In one case report, a patient had elevated levels of FGF-23, which is associated with the development of osteomalacia." (PMID 41000307, 2025). "Burosumab is a monoclonal antibody targeting FGF-23 approved for the treatment of X-linked hypophosphatemia and tumor-induced osteomalacia." (PMID 41008628, 2025). "The resulting elevated FGF23 and low-to-normal levels of 1,25(OH)2D cause phosphate wasting, rickets, and osteomalacia, typically leading to soft and undermineralized bones and tooth dentin." (PMID 39896117, 2025). "Burosumab, a human immunoglobulin G1 monoclonal antibody that targets fibroblast growth factor 23 (FGF23), was developed to treat X-linked hypophosphatemic rickets/osteomalacia (XLH)." (PMID 40978851, 2025). "We propose that the improved renal phosphate reabsorption and vitamin D synthesis associated with burosumab-mediated inhibition of FGF23 results in better healing of rickets and osteomalacia, which are fundamental for correcting lower limb malalignment." (PMID 40511857, 2025). "As such, tumour-associated overexpression of FGF23 can result in tumour-induced osteomalacia or oncogenic hypophosphatemic osteomalacia." (PMID 38397231, 2024). "Elevated levels of fibroblast growth factor 23 (FGF-23) have been demonstrated in tumors from patients with oncogenic osteomalacia and in patients with X-linked hypophosphatemia, leading to increased urinary phosphate loss." (PMID 39803160, 2024). "Most cases of vitamin D‐resistant osteomalacia are caused by overproduction of FGF23, a hormone that promotes urinary excretion of phosphate, resulting in low serum phosphate levels and impaired bone calcification." (PMID 38050660, 2024). "In this paraneoplastic syndrome, the increased production of FGF23, in line with its main endocrine effects, induces renal phosphate excretion and reduction of 1,25(OH)2D3, causing osteomalacia and demineralised bone." (PMID 38397231, 2024). "It is the most common form of hereditary rickets and osteomalacia, while other genetic factors can also contribute to hypophosphatemic rickets, including mutations in FGF23, DMP1, ENPP1, and FAM20C." (PMID 39211452, 2024). "Hereditary hypophosphatemic disorders are associated with FGF23 excess, impaired skeletal growth, and osteomalacia." (PMID 37943605, 2023). "Osteocytes also express PHEX, DMP1, ENPP1, and FAM20C, and inactivating mutations cause FGF23-related hypophosphatemic rickets/osteomalacia." (PMID 36246908, 2022). "As an excess amount of circulating FGF23 is associated with ADHR/osteomalacia, several drug discovery studies have targeted FGF23." (PMID 35159314, 2022). "FGF23 was originally identified in 2000 through a gene mutation in patients with hypophosphatemic rickets and osteomalacia that causes an elevation in the FGF23 level." (PMID 35736431, 2022). "Further FGF23-associated diseases for which anti-FGF23 therapy is tested include tumor-induced osteomalacia." (PMID 35084563, 2022).